CD4 (CD4 molecule)
Diseases named in the same sentence as CD4 in open-access papers (continued):
Sharing a sentence is not in itself a finding about the gene and the disease.
tumor (continued). "Another murine study, using an anti-CD40 agonist, found that increased tumour density was vital to its efficacy, which was dependent on CD8+ T-cells and independent of CD4+ T-cell help." (PMID 34960140, 2021). "Here, we determined the maximum number of CD4+ and CD8+ T cells from WT that would clear the tumour without inducing GVHD." (PMID 34919342, 2021). "We also observed that the immune-mediated delay in KPN1.1 tumor growth was dependent upon CD8 T cells, but not CD4 or B cells (data not shown)." (PMID 34632444, 2021). "In this context, Tregs are capable of suppressing the anti-tumor functions of CD4, CD8, and NK cells, leading to an absence of effective anti-tumor immune response." (PMID 33498483, 2021). "While both unleash exhausted CD8 T cell responses, irrespective of the tumor type, anti-CTLA-4 antibodies additionally modulate the CD4 T cell effector compartment, by expanding an effector ICOS+ CD4 T cell subset." (PMID 34064410, 2021). "In early vaccine trials, when candidate tumor-relevant MHC-class II peptides were not yet identified, attempts to provide CD4+ T cell help were carried out by providing foreign proteins like keyhole limpet hemocyanin or tetanus toxoid." (PMID 33546283, 2021). "LLC/N mice showed a reduced CD4/CD8 ratio in the aged group, but this was not affected by the presence of the tumor." (PMID 35008253, 2021). "Tumor-infiltrating lymphocyte (TIL) analysis revealed that the proportions, but not activation or cytotoxicity, of CD4+ and CD8+ T cells were significantly decreased in Ankrd52-null tumors." (PMID 34853298, 2021). "G47Δ treatment of a syngeneic bilateral hepatoma model inhibited both injected and non-injected tumors, increased tumor-specific IFNγ splenocytes in vitro, and significantly increased CD8+ but not CD4+ T cells." (PMID 34578321, 2021). "Unlike in tumor, there was no significant changes of CD45+, CD3+, CD4+T and CD8+T proportion in Spleen and Lymph Nodes for both BT942 and their combination except for CD8+ population percentage in Spleen by combination." (PMID 34824364, 2021). "TIM-3 is a negative co-stimulatory molecule expressed on CD4+ Th1, CD8+ T cells, Tregs, and other tumor cells." (PMID 33804419, 2021). "In B6 mice injected with PDVC57 tumors, nor-NOHA application increased CD4+ and CD8+ T cells, as well as CD11c+ MHCII+ dendritic cells within the tumor." (PMID 34031449, 2021). "On the other side, median CD4 and mean CD8 were not statistically different between AR− and AR+ tumours." (PMID 35047068, 2021). "Although the tumor Treg proportion was not increased due to the infection in the PLN from infected mice, we detected a higher proportion of CD4+/Foxp3+ Treg cells in the PLNs of both T. canis-infected mice and the 4T1+T." (PMID 32547942, 2020). "In mouse models lacking CD4+ T lymphocytes (CD4–/–) or CD8 T lymphocytes (CD8–/–) through genetic knockout, it was found that blockade of CTLA-4 and PD-1 facilitated tumor vessel normalization by the activation of CD4+ Th1 cells." (PMID 32983126, 2020). "Overall, the ratio of patients with higher dysfunctional populations of both CD4 T and CD8 T cells was significantly higher in those with higher (16/29, 55.2%) rather than lower tumour grade (16/58, 23.5%) (P = 0.004)." (PMID 32277125, 2020). "There was no statistical difference in the densities of CD4+FOXP3+ T cells, DNT cells, CD56+ cells and lineage− cells between the tumor core and edge." (PMID 32377339, 2020). "The E2F6 expression in LGG showed a significant positive correlation with tumor purity and infiltrating levels of B cells, CD8+ T cells, macrophages, neutrophils, and dendritic cells but not with CD4+ T cells." (PMID 33381564, 2020). "As it is not possible to distinguish between the CD4+ T cells with low and high expression of FOXP3 in tumor tissues by conventional immunohistochemistry, this remains a limitation of our study." (PMID 32377339, 2020).
tumor (continued). "In the same study, somatotroph tumours were shown to have a higher number of infiltrating CD4+ and CD8+ TILs compared with non-somatotroph tumours." (PMID 31875303, 2020). "The tumor inhibition and extended survival were attributed to increased infiltration of CD3+CD4+CD44+ immune cells and not suppression of MYC." (PMID 33178203, 2020). "Patients with disseminated tumor cells in their BM had more memory CD4+ T cells and more CD56+CD8+ cells than patients with tumor cell-negative BM." (PMID 32221812, 2020). "Immune checkpoint (PD-1, LAG-3 and TIM-3)-positive CD4+ and CD8+ T cells cannot exert an anti-tumor effect and are regarded as nonfunctional or exhausted subsets." (PMID 32457755, 2020). "In the present case, the pathomorphological examination was nonspecific, but IHC showed positive for EBER, MPO, CD4, BCL-2, CD117, which hinted that tumor cells were from the myeloid cells." (PMID 33120806, 2020). "T-bet expression was not altered by Blimp-1 deletion in activated CD4+ T cells, suggesting the Th1 program does not require Blimp-1, while the cytotoxic program (in both CD4+ and CD8+ T cells) depends on Blimp-1, which is critical for tumor control." (PMID 31924474, 2020). "Using an unsupervised data analysis, we identified eight main clusters, including B cells, Tconvs, Tregs, CD8+ T cells, no CD4+ CD8+ T cells, fibroblast/endothelial cells, tumor cells, and other leukocytes." (PMID 32601304, 2020). "Interestingly, chronic immunotherapy with cytokine-loaded microspheres could not control tumor burden due to a progressive decline in the intensity of antitumor T cells and an increase in tumor-infiltrating CD4+CD25+Foxp3+ T suppressor cells with repeated injections." (PMID 33178203, 2020). "In addition to high SCARF1 expression correlating with a good outcome, our functional assays also suggest that SCARF1 may have an active anti-tumoral role for by promoting the recruitment of effector CD4+ T cells rather than tumor promoting regulatory T cells (Tregs)." (PMID 34354939, 2020). "As for the adaptive populations in the tumor milieu, statistically, differences were observed in T lymphocyte CD3+, B cells CD19+, and T cytotoxic CD8+, but not in T helper (CD4+) or Treg cells." (PMID 32547942, 2020). "In this setting, anti-PD-1 monotherapy decreased the level of PD-1 expression on CD4+ and CD8+ T cells but failed to increase CD8+ infiltration and effector functions in the tumor microenvironment." (PMID 32983966, 2020). "While mPEG/pmIL-12 polymersomes did not affect CD3+CD4+ cells in the tumor, there was a 2-fold increase of CD3+CD8+ cells and significant increases of CD3−NK1.1+ and CD3+NK1.1+ cells in the tumor." (PMID 33178203, 2020). "Percent of CD4+ or CD8+ T cell specific to TERT1, TERT6, or TERT8 did not correlate with either photon flux from tumors by day 16 or tumor size by the experimental end point (all p values >0.05; data not shown)." (PMID 32570805, 2020). "In tumor-bearing mice treated with CTX, the gram-negative Barnesiella intestinihominis, residing in the colon, induced systemic CD4+ Th1 cells and type 1 CD8+ T (Tc1) cells and increased the proportion of intratumoral IFN-γ-producing γδT cells." (PMID 33062956, 2020). "The overall percentage of CD4+ and CD8+ T-cells was not affected by either pembrolizumab or vorinostat treatment and did not predict response in tumor." (PMID 32681091, 2020). "Flow cytometry analyses of cells isolated from CT26 tumors on day 13 indicated that 45 ± 3% of the CD4+ TILs were Tregs (FOXP3+), and 54 ± 2% of the tumor-infiltrating Tregs expressed GARP, regardless of the treatment." (PMID 32917858, 2020). "Intratumoral activation and effector T cell function were also markedly compromised in the absence of NK cells, as revealed by the enumeration of tumor-infiltrating CD44+ CD8+ T cells and IFN-γ-producing CD8+ or CD4+ T cells." (PMID 33220234, 2020).
tumor (continued). "When comparing the cellular fractions between the Cx3cr1‐Rheb1Δ/Δ and Rheb1fl/fl GL261 tumours, a significant increase in CD8 cytotoxic T lymphocytes (CTL) and CD4 helper T (Th) cells was detected, with no changes in regulatory T (Treg) cells (Fig EV3D)." (PMID 32567735, 2020). "As well as dampening oncogenic signaling in tumor cells, MEK1/2 inhibitors increase the number of CD4+ and CD8+ TILs without restraining their effector function." (PMID 32570952, 2020). "The network is generic and will be made specific to different cell types (CD4+ or CD8+), cell conditions (treated or non-treated), and localization (in the lymph node or in the tumour microenvironment) based on specific sets of initial conditions." (PMID 33276543, 2020). "In the MZL tumor samples in contrast, HRG expression did not correlate with an increased presence of CD4+ or CD8+ T cells, or CD68+ macrophages." (PMID 35847718, 2020). "According to the IHC results, there was a striking intratumoral CD4+ and CD8+ T‐cell infiltration restricted to the tumor margin in the primary and lung metastatic lesions, but not in the liver metastatic lesions." (PMID 32994998, 2020). "In vivo depletion experiments demonstrated that CD4 and CD8 cells, but not NK cells, were important in the inhibition of tumor growth triggered by SK1 silencing." (PMID 31974367, 2020). "The percentage of positive cells for all activation markers on both CD4 and CD8 T-cells was highest in primary tumour followed by sentinel node, non-sentinel node and blood." (PMID 33339891, 2020). "CD4 helper T cells, although not prognostic alone, have been recently shown to play an essential role in assisting CD8 T cell anti-tumour responses in many cancer types." (PMID 32582553, 2020). "Using the novel ISAT algorithm, we observed that a high number of CD4+FOXP3+ T cells interacting closely with CD8+ T cells, but not the tumor cells." (PMID 32377339, 2020). "• Both ipilimumab and tremelimumab increase the infiltration of CD4+ and CD8+ cells without significantly changing or depleting FOXP3 cells within the tumor microenvironment." (PMID 32265933, 2020). "This was primarily reflected by a significant decrease in the CD3−CD56+ NK cell compartment (p = 0.0005), while no clear trend was observed between tumor-infiltrating and peripheral CD3+ bulk T cells, CD3+CD4+ and CD3+ CD8+ T cells." (PMID 32082316, 2020). "For the final diagnosis, immunohistochemistry (IHC) was performed, and the tumor cells tested positive for MPO, CD4, BCL-2, KI-67, and CD117 and negative for CD3, CD5, CD20, CD56, bcl-6, Mum-1, CD123, MUM-1, TdT, Syn, SOX11, and C-myc." (PMID 33120806, 2020). "No expression differences in CD3, CD4, CD8, and PD-L1 at the center of the tumor (CT) or invasive margin (IM) were found between patients with stage I&II and stage III&IV dMMR." (PMID 32767974, 2020). "We observed that decreased expressions of EMT- related proteins in the primary tumors, and accumulation of CD4+ and CD8+ T cells and other immune cells in the non-irradiated secondary tumors, as well as a significant inhibition of tumor growth." (PMID 32365904, 2020). "The results clearly indicated that the depletion of either naive CD4+ or naïve CD8+ T cells, but not B cells or NK cells, abrogated the protection against live CIITA-tumor cells." (PMID 33138029, 2020). "No change was found in tumor-infiltrating CD4+ or CD8+ T cells or macrophages, while a trend toward a reduction in tumor-infiltrating Tregs was observed." (PMID 33134306, 2020). "We present a novel model posing that virus-specific or tumor-specific, predysfunctional TCF-1+ CD8+ T cells in chronic infection or cancer result from priming in the absence of CD4+ T cell help." (PMID 33123174, 2020). "Multiplex IHC showed all three types of tumor had infiltration of CD8 T cells, non-regulatory CD4 T cells and Tregs." (PMID 32937841, 2020).
tumor (continued). "In different experimental models, it was shown that an exclusive tumor Ag-specific CD8+ T cell response, in the absence of an antitumoral CD4+ T cell response, cannot establish long-lasting memory." (PMID 32582212, 2020). "Unlike anti-PD-1 treatment, TRIMELVax induced potent tumor infiltration of CD8+ T cells, being CD8+/CD4+ T-cell ratio significantly enhanced by TRIMELVax." (PMID 32690772, 2020). "The CD4+ T cells and CD8+ T cells populations in spleen, thymus, and tumor have not been changed after AS treatments." (PMID 31293425, 2019). "The TNF family receptor Fas was recently found to promote terminal differentiation of CD4+ and CD8+ T cells, while non-apoptotic Fas signaling induces tumor cell growth and impairs the efficacy of T cell adoptive immunotherapy." (PMID 31703694, 2019). "The resulting TILs (after 3× stimulation with autologous tumour cells) were enriched for CD8+ TILs (almost 100%), while CD4+ T cells were entirely absent (from 22% pre-stimulation to 0% post-stimulation with tumour cells) based on flow cytometric data." (PMID 30377343, 2019). "In tumor bearing mice, crizotinib increased the expression of the PD-1 (and LAG-3 but neither CTLA-4 nor TIM-3) on circulating CD4+ or CD8+ T lymphocytes." (PMID 30940805, 2019). "Neither the genotype nor the treatment had an influence on CD4+ and CD8+ T cell frequencies in spleen and tumor; however, poly(I:C)c failed to induce CD69 expression in T cells of Ifnar1−/− mice." (PMID 31694706, 2019). "Here, FR+ and FR-negative tumor cells without or with EC17 pre-loading (0.1 or 10 nM, 30 min pulse at 37°C) were incubated with EGFRt-sorted CAR-T cells (1:1 CD4/CD8) at an E/T ratio of 1:2." (PMID 30941303, 2019). "Depletion of either CD4+ or CD8+ T lymphocytes (confirmed by flow cytometry, data not shown), resulted in effective tumor growth." (PMID 30546090, 2019). "NK and CD4+ T cells, but not CD8+ T cells, were essential to dual-function therapy-mediated effective tumor suppression, and CD4+ T cells provided help for the activation of NK cell by production of Th1 or Th2 cytokines." (PMID 31849942, 2019). "Other leukocytes, such as CD4 T cells, Foxp3+ Tregs, CD8 T cells, and dendritic cells, in the tumor stroma were not affected by MEL or MEL-dKLA treatment." (PMID 31174610, 2019). "Tumor-bearing mice with low C5a-producing tumor cells exhibit a reduced tumor burden with increased IFN-γ-producing CD4+ and CD8+ T cells in the spleen and tumor-draining lymph nodes." (PMID 31031765, 2019). "Unlike the innate response, tumor-specific CD8+ and CD4+ T cells proliferate in an antigen-specific manner following stimulation by APCs." (PMID 30974896, 2019). "We also found that the tumors in CD4+ T cell–depleted mice grew very poorly, with or without SLR14 treatment, likely reflecting T reg depletion leading to tumor control." (PMID 31601678, 2019). "In contrast, high concentration (100 ng/ml) of IL-24 stimulation promoted both CD4+ and CD8+ T cell function, which presented as increase of Th1/Th17 cells and elevation of cytolytic and non-cytolytic activity of peripheral and tumor-infiltrating CD8+ T cells." (PMID 31921658, 2019). "These CD4+ T cells expressed Eomes but not T-bet, secreted IFN-γ, expressed granzyme B and perforin, and were capable of lysing autologous tumor cells." (PMID 31379821, 2019). "Notable, a majority of tumor cell types do not express MHC class II, and, because of that, escape direct elimination by cytotoxic CD4+ T cells." (PMID 31437237, 2019). "There were trends for increased CD4 and CD8 T cell signatures in the tumor with increased adjusted maximum fitness cost (data not shown)." (PMID 31849976, 2019). "We found that both CD4+ and CD8+ T cells, at least, infiltrated not only the tumor bed at the irradiated site but also the non-irradiated site." (PMID 31058025, 2019).
tumor (continued). "The immunodepletion of any of NK cells, CD4+ T cells or CD8+ T cells, diminished anti-tumor effects induced by eMIP, indicating that these lymphocyte subsets play essential roles in tumor regression at both treated and non-treated sites." (PMID 31058025, 2019). "In this model, we did not see an appreciable infiltration of CD4+ T, CD8+ T or CD161/KLRB1+ natural killer (NK) cells in the bladder/tumor." (PMID 30654801, 2019). "In contrast CD4 CTLs recognize class II MHC molecules, which are usually absent in normal nonimmune cells, but present in a subset of tumor cells." (PMID 31719197, 2019). "The percentages of CD28 negative cells were lower between CD4+ (but not CD8+) T cells from spleens and LN of fully recovered mice compared to tumor-free mice." (PMID 31717542, 2019). "In the absence of T cells or in the presence of only CD4+ or CD8+ T cells, TNFα‐CSG treatment did not significantly reduce tumour weight and volume." (PMID 31709774, 2019). "There was no change in the percentage of CD4+, CD8+, and γδ T cell in the spleen and tumor of DMSO control, α-GalCer or α-GalCer plus anti-NK1.1 mAb-treated tumor-bearing mice (data not shown)." (PMID 31387637, 2019). "In the current study, the high density of CD4+ T cells and Foxp3+ Treg cells, but not CD8+ T cells, in the tumor microenvironment was positively correlated with better PFS." (PMID 30978241, 2019). "We found that a low CD8:CD4 ratio is associated with higher Ki-67, suggesting that relatively low CD8+ to high CD4+ T cells, rather than absolute CD8+ and CD4+ T cell amounts per se, represent a relative imbalance potentially affecting tumour proliferation." (PMID 31703742, 2019). "Our data also confirm that electroporation of the tumors can modify the proportions of Tef/Tem and Tcm CD4 and CD8 T cells in spleen and lymph nodes, but not between tumor-infiltrated lymphocytes." (PMID 31717542, 2019). "An OX40/CD137-specific mAb2 can autonomously stimulate both CD4+ and CD8+ T cells in vitro independent of FcγR binding and mediate potent anti-tumour activity in vivo via an FcγR-independent mechanism of action." (PMID 30400822, 2018). "A negative correlation between tumor size and the abundance of both CD3+ (r2 = –0.87, p < 0.0001), CD8+ (r2 = –0.84, p < 0.0001), CD4+ (r2 = –0.85, p < 0.0001) and FOXP3+ (r2 = –0.88, p < 0.0001) cells was observed." (PMID 30687269, 2018). "Inoculation of MDSCs loaded with α-GalCer and tumor antigen induced protective tumor immunity dependent on CD8+ T cells, NK cells, and type I NKT cells, but not CD4+ T cells and host DCs." (PMID 30158927, 2018). "This indicates that Vγ6+ T cells are actively responding to oxidative damage, unlike CD4+ and CD8+ T cells, which are largely unchanged by the presence of neutrophils in the tumor microenvironment." (PMID 29750788, 2018). "Despite the decreased-percentage of PD1 positive cells and Foxp3 positive cells in CD4+ and CD8+ T cells following treatment with EP1 or EP2 without pIL-12, tumor growth continued in EP1 and EP2 groups." (PMID 30544810, 2018). "Most tumours do not express MHC-II, but CD4 T-cells are initially activated by tumour infiltrating antigen presenting cells (APCs) that constitutively undergo autophagy and express MHC II." (PMID 29570634, 2018). "In these models, conventional CD4+ and CD8+ T cell infiltration were maintained suggesting that CCR5 expression on the surface of these cells is not required for tumor infiltration." (PMID 30420855, 2018). "By contrast, CD4−, CD8−, but PD-1+, CD45+ tumor-infiltrating lymphocytes have no impact on OS and PFS (P = 0.073 and P = 0.249, respectively)." (PMID 29910795, 2018). "Further investigation of the TILs in the 50 patients with G1/G2/G3 NETs showed that the levels of CD3+/CD4, and CD3+/CD8 TILs were not different, but those of CD3+/PD-1high and CD204+/PD-L1high populations were significantly higher in higher grade NET tumours." (PMID 30177687, 2018).